MSLN (mesothelin)
Diseases named in the same sentence as MSLN in open-access papers (continued):
Sharing a sentence is not in itself a finding about the gene and the disease.
tumor (continued). "In one case (autopsy, No. 70) which showed only a few nuclei with positive IR for Calretinin and positive membranous IR for EMA in less than 25% of cells, the combination Podoplanin and Mesothelin, with IR in two and three quartiles of tumour cells, respectively, would have been a better option." (PMID 20602796, 2010). "The expressions of mesothelin in chemosensitive EOC patients with residual tumour size ⩽1 or >1 cm were significantly lower than those in the chemoresistant groups, which indicates that mesothelin can be a potential biomarker to evaluate chemotherapeutic effects on EOC patients." (PMID 19293794, 2009). "The interaction of mesothelin and MUC16 may enhance the physical association of tumor cells and contribute to spheroid formation." (PMID 17067392, 2006). "However, current understanding remains largely confined to cell line and animal models, and the regulatory networks of MSLN within the complex human tumor microenvironment, as well as its functional heterogeneity across different cancer types, require further clinical validation." (PMID 41400642, 2025). "Therefore, MSLN has become an attractive target for tumor‐specific therapy." (PMID 39887656, 2025). "In addition, a significant reduction of MSLN-positive tumor masses was observed in mice treated with a combination of MSLN490 and standard chemotherapeutics (i.e., paclitaxel), suggesting that this strategy is promising even for solid tumors with low immune cell infiltration." (PMID 41335396, 2025). "However, anti-MSLN CAR-like NK cells demonstrated a greater advantage in reducing the tumor burden." (PMID 41436559, 2025). "Thus, restoring miR-198 expression can downregulate mesothelin, inhibiting tumor progression." (PMID 40227616, 2025). "Therefore, in-depth research into the regulation of various immune cells by MSLN and its interactions with other components in the tumor microenvironment will greatly deepen our understanding of tumor immune escape and open up new avenues for developing MSLN-based immunotherapies." (PMID 41400642, 2025). "In patients with advanced disease, MSLN is associated with poor survival outcomes, regardless of whether or not they have undergone tumor cytoreductive surgery." (PMID 41400642, 2025). "When we investigated the effects of tumor-derived EVs on naïve neutrophils, we observed that even a short exposure to EVs from tazemetostat-treated cells prompted a shift in these neutrophils toward a protumor phenotype, marked by elevated levels of PD-L1 and MSLN on their surface." (PMID 41226368, 2025). "In this study, we aimed to better characterize mesothelin expression in PCa and PCa models, and to evaluate the therapeutic potential of second-generation meso-CAR-T cells under both normoxic and hypoxic conditions, with hypoxia simulating a tumor-associated stress." (PMID 40427042, 2025). "Additionally, MSLN expression was high in transverse tumor locations in both patient cohorts." (PMID 39174744, 2024). "Compared with those in the anti-MSLN CAR-T-cell+PD-1 mAb and anti-MSLN CAR-T control groups, PD-1-disrupted anti-MSLN CAR-T cells could better inhibit the growth of tumor cells and had a stronger ability to prevent recurrence, which may be related to the degree of T-cell exhaustion." (PMID 39023820, 2024). "MSLN may provide a growth advantage for tumor cells in the early stage of tumor metastasis seeding." (PMID 39023820, 2024). "Furthermore, we examined the phenotype of anti-MSLN CAR-T cells after co-culture with tumor cells." (PMID 37359558, 2023). "Recently, the modified anti-ERC/mesothelin therapies have been developed to enhance its anti-tumor activities, and these new agents include antibodies linked to Pseudomonas exotoxin, or those conjugated with a tubulin inhibitor, or anti-ERC/mesothelin CAR-T cells." (PMID 35565327, 2022).
tumor (continued). "However, measurement of mesothelin alone is considered insufficient as a sensitive indicator of tumor progression, which has prompted the search for additional molecules that could be combined to establish a biomarker signature with prognostic value." (PMID 36303838, 2022). "The discovery of novel MSLN dual-targeted drugs that could mimic the deletion of host MSLN expression, such as antibody-conjugates and vaccines, and be cytotoxic to tumor cells would be ideal to improve survival in OvCa and other cancers with MSLN overexpression." (PMID 34830322, 2021). "Besides, mesothelin-accelerated tumor progression is accelerated by CA125." (PMID 33832498, 2021). "Therefore, MSLN that accumulates in the tumor extracellular fluid after shedding could potentially act as a decoy receptor that limits iTox activity." (PMID 32605175, 2020). "The antigens derived from the aberrantly overexpressed self-antigens in tumor cells compared to normal cells (e.g., RAGE-1, hTERT, HER2, mesothelin, and MUC-1) are defined as tumor-associated antigens (TAAs) and might represent universal antigens among patients with the same malignancy." (PMID 33080888, 2020). "However, a favorable treatment outcome requires strong Mesothelin expression in tumor cells." (PMID 32815024, 2020). "In addition, we evaluated the expression of MSLN in four specific areas (i.e., submucosa, subserosa, central area, and superficial tumor area) by immunohistochemical staining and found that MSLN expression exhibits little heterogeneity and correlates with poorer prognosis regardless of the area." (PMID 33196692, 2020). "Notably, the traditional second-generation CAR-T cells exhibited strong cytolytic effects toward tumor as well as toward normal cells expressing the only mesothelin, partially causing serious adverse reactions, whereas dual-signaling CAR-T cells showed selective specificity for tumor cells." (PMID 31783889, 2019). "In contrast to the negative effect of shed MSLN in blood circulation, a mathematical simulation suggested that the shed MSLN in the extracellular space (ECS) could positively affect the tumor uptake by improving the penetration of the antibody toward tumor core." (PMID 29720923, 2018). "This suggested that an immune response to mesothelin might be effective in reducing tumor growth." (PMID 29474384, 2018). "In addition, depletion of T regulatory cells may counteract homeostatic or cancer cell driven immunosuppression and enhance the development of mesothelin-specific CD8 T cells capable of killing tumor cells." (PMID 29474384, 2018). "In contrast, tumor and organ uptakes of 89Zr-amatuximab were dose-dependent, whereby a high dose (60 μg) was needed to achieve tumor targeting comparable to the low dose (2 μg) of 89Zr-B3, suggesting that shed mesothelin may affect amatuximab tumor targeting as well as serum half-life." (PMID 29720923, 2018). "Hence, dCAR-engineered T cells have no any cytotoxicity for normal tissues expressing only the tumor-associated antigen MSLN." (PMID 30103775, 2018). "Therefore, we reformatted amatuximab and HN1 scFvs as BsAbs to target EDV to MSLN-positive tumours." (PMID 29059207, 2017). "Here miR-21-5p appears to act as a tumour suppressor miRNA since it negatively regulated an oncogene (MSLN), and this could be explained considering that miRNAs could play different roles depending on the pattern of their target mRNAs expressed in that specific cancer type or tissue." (PMID 28125734, 2017). "Therefore, we investigated whether abundance of CA-125 can negatively affect the ability of RG7787 to bind to and be taken up by mesothelin-positive tumor cells, thereby potentially preventing therapeutic success." (PMID 29273809, 2017). "Furthermore, siRNA specific for mesothelin suppressed tumor growth in a rat renal carcinoma model." (PMID 26931187, 2016).
tumor (continued). "To determine whether mesothelin overexpression reduced tumor growth or if this might be due to the particular promoter or plasmid construct, we also assessed mesothelin ing Panc02 clones constructed using the retroviral (RV) transduction system with mesothelin under the LTR promoter." (PMID 26931187, 2016). "Therefore, the different anti-tumor activities (IC50s) of different immunotoxins may be attributed to their different binding affinities for mesothelin instead of their different epitopes." (PMID 25996440, 2015). "However, recent studies indicate that MSLN may play an important role in cell adherence, cell survival/proliferation, tumor progression, and chemoresistance." (PMID 25883990, 2015). "However, also for the lower percentages of MSLN over-expressing tumors within other tumor types over-expression of MSLN could be an interesting target." (PMID 26172299, 2015). "The precise dosing of drugs and selection of patients for mesothelin directed therapy could benefit from non-invasive visualization of anti-mesothelin antibody (AMA) to quantify antibody uptake in tumor lesions, and ultimately to relate this to anti-tumor effects of mesothelin-targeting ADC." (PMID 26536664, 2015). "As the clinical utility of the cytological diagnosis of MM has been called into question, the concomitant analysis of effusion tumour markers including mesothelin, CEA, Cyfra21-1, and others either alone or in combination may be a way to improve the clinical uptake of effusion-based MM diagnosis." (PMID 25505814, 2014). "Additionally, tumor vaccines targeted against mesothelin are currently being studied." (PMID 24024776, 2013). "However, whether MSLN acts a role for tumor’s distant organ metastasis remains unclear." (PMID 41513618, 2026). "The local inhibitory checkpoint monoclonal antibody (LicMAb) binds mesothelin (MSLN) with high affinity and simultaneously blocks CD47 on MSLN-expressing tumor cells to inhibit the “don’t eat me” signal." (PMID 40402266, 2025). "Conversely, the knockdown of MSLN expression reverses EMT, restores the expression of epithelial markers, and effectively inhibits tumor cell migration." (PMID 41400642, 2025). "Second, the presence of MSLN(+)CTCs or CTCs detection in a few patients with benign lesions may be related to the specificity limitation of the detection method, or it may be that tumor cells do exist in the patient’s body, and such patients should be followed up closely for confirmation." (PMID 40792273, 2025). "MSLN is an ideal therapeutic target due to its nearly 100% expression rate in MPM and its correlation with tumor aggressiveness." (PMID 40969260, 2025). "In conclusion, mesothelin uses the PI3K/Akt and MAPK pathways to promote tumor growth and immune evasion." (PMID 40227645, 2025). "In TNBC models, bispecific or dual-target CAR-T designs, such as those targeting B7-H3/CSPG4 or mesothelin/NKG2D ligands, have demonstrated potent cytotoxicity and superior tumor regression compared with single-target CAR-T approaches." (PMID 41348261, 2025). "In contrast, NKG2D/CD28& MSLN CAR-T cells maintained robust antitumor activity in this low-density antigen context, leading to complete tumor clearance in all mice." (PMID 40181405, 2025). "MSLN enhances the expression and phosphorylation of MET via the JNK signaling pathway, thereby increasing the ability of tumor cells to penetrate the blood-brain barrier." (PMID 41400642, 2025). "Specifically, responsive organoids (N = 6) showed low MSLN expression, and an abundance of cytotoxic CD8 + T-cells and tumor-suppressive TAM expressing high HLA-DR, CD86, and CXCL9." (PMID 41335396, 2025). "When MSLN is knocked down in PM, stem cell and epithelial–mesenchymal transition (EMT) genes are downregulated, which reduces tumor development and metastasis in vivo." (PMID 40227645, 2025).
tumor (continued). "The anti-MSLN Fv ensures tumor-specific targeting, while PE38 exerts its cytotoxic effect (blocking protein synthesis and inducing apoptosis) upon internalization into MSLN-overexpressing cancer cells." (PMID 41335396, 2025). "For instance, the HN1 antibody, which targets full-length MSLN, not only effectively inhibits the binding of MSLN to MUC16 but also induces cell death in MSLN-positive tumor cells through its antibody-dependent cellular cytotoxicity (ADCC) mechanism." (PMID 41400642, 2025). "As a potential target in the nanovaccine approach, we verified the expression of the tumor antigen MSLN in murine PDAC KPC cells and tumor samples from both PDAC patients and mice, confirming that MSLN represents a suitable antigen target for vaccination." (PMID 40266223, 2025). "To overcome these limitations, we developed anti-mesothelin (MSLN) uCAR-like NK cells, which are designed to enhance both the targeting specificity and tumor infiltration capacity, thereby improving the antitumor efficacy of NK cell-based therapies." (PMID 41436559, 2025). "Because MSLN can bind to MUC16 on other tumor cells, it has been demonstrated that the MSLN–MUC16 relationship is crucial for tumor cell adhesion and metastasis." (PMID 40227645, 2025). "Specific instances of trogocytosis include the transfer of tumor antigens such as CD19, mesothelin, BCMA, and NKG2D ligands onto CAR-T or CAR-engineered NK (CAR-NK) cells." (PMID 41194129, 2025). "After washing, anti-MSLN CAR-like NK cells recognize and kill tumor cells due to the stable anchoring of MSLN×CD16A on their surface, with an efficacy comparable to that of MSLN×CD16A combined with CIML NK cell therapy." (PMID 41436559, 2025). "Several CAR-T cell therapies are targeting EGFR, MUC1, and mesothelin (MSLN), and other tumor antigens and are being tested in early-phase clinical trials." (PMID 41373672, 2025). "To further validate our observation, we also treated anti-mesothelin (MSLN) CAR-T cells with sodium citrate and detected the phenotypes and anti-tumor function of CAR-T cells." (PMID 40165944, 2025). "Clinical studies have demonstrated that the co-expression of MSLN and MUC16 is significantly correlated with tumor progression, adversely affecting patient prognosis." (PMID 41400642, 2025). "It has been suggested that RT, in conjunction with MSLN-targeting CAR-T treatment, represents a viable strategy for enhancing tumor microenvironment modulation, CAR-T cell trafficking and anti-cancer effects in patients with unresectable PDAC." (PMID 40227616, 2025). "Exosomes derived from mesothelin (MSLN)‐targeted CAR‐T cells have been shown to effectively target MSLN‐positive TNBC cells and inhibit tumour growth by secreting perforin and granzyme B." (PMID 40032646, 2025). "Mesothelin (MSLN) is a GPI-anchored membrane glycoprotein expressed on mesothelial cells in the pleura, peritoneum, and pericardium and is involved in tumor differentiation." (PMID 40514426, 2025). "In this study, we demonstrated that anti-MSLN CAR-like NK cells exhibit potent and specific activity against MSLN-positive tumor cell lines and effectively inhibit tumor growth in xenograft mouse models." (PMID 41436559, 2025). "Mesothelin-specific CAR-T targets the cell surface antigen mesothelin, which is overexpressed in many solid tumors, with limited expression in non-tumor tissue." (PMID 40872551, 2025). "We found the MSLN expression on CD45-negative cells in the HSV-MSLN-treated group, reaching around 20% in both Pan02 and KPC tumor-bearing mice." (PMID 40366419, 2025). "This suggests that MSLN helps PDAC cells evade senescence by downregulating these critical pathways, thereby promoting tumor progression." (PMID 40563707, 2025). "Early-phase trials targeting EGFR, MSLN (mesothelin), PSCA (prostate stem cell antigen), and MUC1 have shown preliminary evidence of tumor control, albeit with challenges related to trafficking and the immunosuppressive tumor microenvironment." (PMID 41303058, 2025).
tumor (continued). "Our previous studies revealed that MSLN acts as a malignant factor in PDAC by promoting cell proliferation and migration and contributing to tumor progression in different mouse models." (PMID 40563707, 2025). "As described in Section “Mesothelin in tumor pathology and dynamics” of this review, MSLN plays a role in tumor progression and metastasis, and can be found either anchored to the membrane or in its soluble form." (PMID 41335396, 2025). "Anti-MSLN CAR-like NK cells, which only exhibited targeted effects, tended to slow tumor growth and disease progression, but their efficacy was inferior to that of anti-MSLN uCAR-like NK cells with penetrating activity." (PMID 41436559, 2025). "In summary, anti-MSLN CAR-like NK cells not only demonstrate therapeutic feasibility but also exhibit unique antitumor advantages, providing new insights for tumor immunotherapy." (PMID 41436559, 2025). "We then evaluated anti-MSLN uCAR-like NK cells in the HGC27-MCS model, where their improved penetration translated into markedly enhanced tumor-targeted cytotoxicity." (PMID 41436559, 2025). "In this study, the treatment with VIC-008 was found to increase mesothelin-specific CD8+ T cell responses, to promote lymphocytic infiltration in the tumor microenvironment, but also to induce an increased expression of PD-1 in intratumoral CD8+ T lymphocytes." (PMID 40918456, 2025). "Similar to the results of the Pan02 tumor model, both the HSV-MSLN group and the combination group significantly inhibited tumor growth compared to the control and MSLN-CAR T cell groups." (PMID 40366419, 2025). "Together, the role of sodium citrate in reducing exhaustion and enhancing anti-tumor activity is verified in both anti-CD70 and anti-MSLN CAR-T cells." (PMID 40165944, 2025). "Then, LMB-100 (also known as RG7787) was generated by fusing an anti-MSLN Fab to PE24, retaining the same anti-tumor effectiveness as SS1P but with reduced side effects." (PMID 41335396, 2025). "T28zT2 T cells also demonstrated effective suppression of tumor growth in two HCC patient-derived xenograft (PDX) models, and both T28zT2 T cells and anti-MSLN CAR T cells (M28zT2 T cells) effectively inhibited tumor progression in HeLa xenografts." (PMID 40107245, 2025). "Our study provides evidence that MSLN promotes MET expression and activation via the JNK signalling pathway, which helps tumor cells degrade TJs of the BBB, thereby promoting the development of BM." (PMID 38570866, 2024). "Conversely, autologous mesothelin-specific CAR-T cells modified using slow virus transduction have been demonstrated to be safe and have shown potential anti-tumor activity." (PMID 38756774, 2024). "Mesothelin expression promotes the tumorigenicity of human lung cancer by inducing the EMT and stemness of tumor cells." (PMID 39766230, 2024). "Anti-mesothelin CAR-T cells, such as the M28z10 T cells, have been shown to induce tumor regression in various xenograft mouse models of GC." (PMID 39397869, 2024). "This study seeks to correlate MSLN expression with known CRC prognostic signatures, including tumor-sidedness, metastatic sites, and the consensus molecular subtypes (CMS)." (PMID 39174744, 2024). "Lastly, although mesothelin targeted therapeutics have in general shown limited off‐tumour‐on‐target toxicity in clinical trials, it is a concern for highly active CAR T cells that can recognise low level mesothelin expression on normal tissues." (PMID 39548594, 2024). "In this model, combining anti-mesothelin CAR-T cells with 1Gy x 4 fractions or 4Gy x 1 fraction both significantly enhanced tumor control and prolonged survival for up to 75 days after tumor-cell implantation." (PMID 39445067, 2024). "Then we detected the expression of mesothelin as a tumor cell marker and the expression of hCD3 as a CAR-T cell marker in tumor sections from these groups." (PMID 39657666, 2024).